CRH (corticotropin releasing hormone)
Diseases named in the same sentence as CRH in open-access papers (continued):
Sharing a sentence is not in itself a finding about the gene and the disease.
depression (continued). "Treatment with allopregnanolone or treatments that increase allopregnanolone levels exerts antidepressant effects in animal models and decreases CRH expression in the PVN, suggesting that allopregnanolone can decrease the behavioral and neuroendocrine abnormalities associated with depression." (PMID 30906252, 2019). "Thus, hippocampal activity is affected by stressful state, and, particularly in the state of stress-induced depression, the responsiveness of hippocampal neurons can be altered to serotonergic and adrenergic inputs as well as corticotropin releasing hormone (CRH) stimulation." (PMID 28888226, 2017). "Moreover, most previous studies utilizing DEX/CRH test have been based on data obtained from inpatients, which implies a clinical subgroup with severe symptoms, whereas our current sample consisted of a depression severity at the outpatient level." (PMID 27582123, 2016). "Thus, MSH may be elevated in depression due to both low melatonin levels and hypersecretion of CRH, and this could contribute to the presentation of patients with psoriasis." (PMID 26550011, 2015). "The aim of the AGENDA trial was to investigate whether long-term intervention with SSRI versus placebo affects the cortisol response in the dexamethasone corticotropin-releasing hormone (DEX-CRH) test in healthy first-degree relatives to patients with major depressive disorder (MDD)." (PMID 21738622, 2011). "Depression is associated with an altered function of the neuroendocrine feedback regulation of the hypothalamic-pituitary-adrenal (HPA) axis, including cortisol escape from dexamethasone suppression and increased cortisol responses to the dexamethasone corticotropin releasing hormone (DEX-CRH) test." (PMID 21738622, 2011). "Our study demonstrates that chronic ATRA treatment upregulates hypothalamic RARα and CRH, key regulators of the hypothalamic–pituitary–adrenal (HPA) axis, leading to depression-like behaviors in rats." (PMID 40900922, 2025). "Our work was informed by the neuroinflammatory theory of depression, because the inflammatory response system activates the HPA axis, leading to the production of corticotropin-releasing hormone (CRH) and adrenocorticotropic hormone (ACTH)." (PMID 39358787, 2024). "Behavioral test results of mice after injection of CORT suggested depression-like behavior, and serum levels of CORT, ACTH, and CRH increased dose-dependently and over time." (PMID 39539631, 2024). "Studies have highlighted the involvement of the hypothalamic–pituitary–adrenal (HPA) axis in depression, demonstrating abnormal activation of the HPA axis and subsequent release of corticotropin-releasing hormone (CRH)." (PMID 38243216, 2024). "Overexpression of CRH and CRHR1 can be regarded as the primary neurobiological correlate of major depressive disorder." (PMID 36624454, 2023). "Most research to date has focused on only one component of the axis (e.g., CRH or cortisol) per study, limiting knowledge of where variations from the norm may originate in the axis, how they evolve as they progress through the axis, and their role in development and severity of depression." (PMID 38149098, 2023). "In mice with breast cancer concurrent with depression, the content of the HPA axis, such as CORT, ACTH, and CRH, were increased." (PMID 35873784, 2022). "These genes are involved in the complex pathological mechanism of depression, including the neurotransmitter system (e.g., HTR2A and SLC6A4), neurotrophin (e.g., BDNF), hypothalamic-pituitary-adrenal (HPA) axis (e.g., CRH), and inflammation (e.g., IL6, TNF)." (PMID 36072347, 2022). "LPS induces oxidative stress and the release of proinflammatory factors, leading to corticotropin-releasing hormone (CCH), elevated serum corticosterone, hypothalamic–pituitary–adrenal axis dysfunction, and depression-like behaviors in animals." (PMID 36339940, 2022).
depression (continued). "The successful establishment of an OD animal model affecting depression was corroborated on days 21 and 56 with the evaluation of body weight, SPF, OFT and EPM behavior results, and circulating CRH, ACTH and CORT levels." (PMID 35741632, 2022). "HPA axis function disorder is closely related to the high level of cortisol of depression patients, and there are three important hormones in HPA axis including corticotropin-releasing hormone (CRH), corticotropin (ACTH) and cortisol." (PMID 36188568, 2022). "Long-term chronic stress can lead to dysfunction of the HPA axis and increased secretion of CRH, ACTH, and CORT, which is considered to be closely involved in the pathogenesis of human depression." (PMID 35237160, 2022). "CRH and ACTH are commonly increased for the depression patients, and play important roles for the imbalance of cortisol." (PMID 36188568, 2022). "CRHR1 mediates the action of corticotropin-releasing hormone (CRH), one of the most extensively studied systems concerning its potential role in stress and depression." (PMID 34831190, 2021). "Acute cytokine administration has been shown to increase corticotropin-releasing hormone (CRH), adrenocorticotropic hormone (ACTH), and cortisol release, all of which have been found to be elevated in patients with major depression." (PMID 30792669, 2019). "Meanwhile, both the AVP and CRH released by the HPA-axis contribute to the signs and symptoms of depression; thus, detecting the hormone concentrations of AVP, CRH and ACTH will be one of our future studies." (PMID 29487521, 2018). "For example, HPA stress responses are initiated by CRH neurones within the PVN and the HPA axis are known to be activated in depressive disorders." (PMID 30034342, 2018). "As similarly discussed in regard to depression, chronic stress results in lasting HPA axis hyperactivity with elevated baseline levels of ACTH, CRH, and cortisol." (PMID 26550011, 2015). "Current evidences suggest that the prednisolone suppression test (PST), in contrast to the DST and the Dex/CRH test, probes both the MR and the GR and hence provides a more valid test of the HPA axis in depression." (PMID 24478730, 2014). "Taken together, these studies support a pivotal role of the central CRH system in mediating the link between ELS and depression, and the genetic moderation of this link." (PMID 24596569, 2014). "In contrast, women with a history of childhood abuse with comorbid major depression exhibited blunted ACTH responses, likely due to chronic overexposure of the pituitary to CRH." (PMID 24695633, 2014). "This antidepressive effect of Xiangshao granule appeared to be related to decreased serum levels of CRH, CORT, and ACTH in the mouse depression model used." (PMID 24367385, 2013). "Pharmacological interventions targeting the neurochemical systems involving NPY, BDNF, CRH, and HPA axis, among others, are being investigated as potential treatments for depression and PTSD." (PMID 23422934, 2013). "CRH and glucocorticoids directly and/or mutually modulate activities of microglia, and activated microglia release pro-inflammatory mediators, which may result in various psychiatric symptoms such as anxiety, fear, and depression beyond the classical understanding of the HPA axis." (PMID 23874274, 2013). "Corticotropin-releasing hormone (CRH) plays an important role in a substantial number of patients with stress-related mental disorders, such as anxiety disorders and depression." (PMID 23882180, 2013). "Serum CRH, CORT, and ACTH levels were significantly increased in depression mice compared with control (P < 0.05) and the expression levels of hippocampal BDNF and TrkB were reduced in the model group (P < 0.05)." (PMID 24367385, 2013). "Beside monoamine neurotransmitters, the serum level of CRH, CORT, and ACTH and changes in levels of GR were being used to evaluate depression." (PMID 23008744, 2012).
depression (continued). "We have also reported heightened HPA axis in major depression and its normalization after treatment as assessed with the combined dexamethasone (DEX)/corticotropin releasing hormone (CRH) test." (PMID 21726461, 2011). "In conclusion, this is the first study on lithium monotherapy for acute unipolar depression in more than 20 years, and the first prospective study of lithium monotherapy to ever use the DEX/CRH test." (PMID 22132117, 2011). "This difference suggests that hypercortisolism in depression may represent a defect at the CRHR level, at least in some patients, resulting in CRH hypersecretion and CRH-NE hyperactivation." (PMID 38092990, 2025). "When cytokines stimulate the HPA axis, the release of stress hormones, including corticotropin-releasing hormone (CRH) and cortisol, may contribute to the onset of depression." (PMID 40808838, 2025). "Animal studies confirm CRH’s pro-convulsant role when injected into the hippocampus, and medications that block CRHR1 are being developed as promising therapies for epilepsy and depression." (PMID 40941042, 2025). "This difference suggests that in depression, hypercortisolism may be due to a defect in the CRHR receptor response with the hypersecretion of CRH and consequently of NE." (PMID 38927393, 2024). "Consequently, it results in elevated levels of ACTH, corticotropin (CORT), CRH, and HPA axis overactivity, ultimately triggering depression." (PMID 37932977, 2023). "Danzhi Xiaoyao powder and Kai Xin San inhibit the hyperactivity of the HPA axis and reverse abnormal activity in depression-model rats, significantly reducing the concentrations of CORT, ACTH, and corticotropin-releasing factor hormone (CRH) in the plasma and hypothalamus." (PMID 37631092, 2023). "It is also important to point out that the dexamethasone-CRH test is abnormal in other forms of non-neoplastic hypercortisolism such as schizophrenia, mania, and certain forms of depression." (PMID 37409223, 2023). "An experimental study examined HPA axis function in perimenopausal women with and without current or past depression using the combined dexamethasone-corticotropin-releasing hormone (Dex/CRH) test." (PMID 38149098, 2023). "In addition, the model provides a mechanism for blunted CRH and elevated DEX-CRH tests in depression." (PMID 38055769, 2023). "Under depression conditions, the expression of GRs decreases, which weakens the inhibition of the HPA axis, leading to the excessive activation of the HPA axis, thereby increasing the levels of CRH, ACTH, CORT, and GC in the patients with depression and affecting the secretion in vivo." (PMID 36973813, 2023). "In major depressive disorder, the glucocorticoid receptors' sensitivity decreased, leading to the reduction in the HPA axis' negative feedback mechanism to maintain homeostasis, which leads to the hypersecretion of CRH, ACTH and cortisol." (PMID 35873784, 2022). "We found that the CRH and HSD11β2 methylation levels were higher in the depression group than those in the non-depression group." (PMID 36184597, 2022). "We found that the CRH and HSD11β2 methylation levels were higher in depression group than non-depression group." (PMID 36184597, 2022). "Our results showed that the methylation level of CRH gene was higher in the D-S group and D-NS group than in the ND-S group, and similar results were observed in comparison of depression group and non-depression group." (PMID 36184597, 2022). "Women who were classified as experiencing financial strain and depression also had elevated CRH levels relative to women who did not report these stressors." (PMID 33824413, 2022). "With the exception of PFNA, the relationship between PFAS and CRH among those who did not experience depression was null." (PMID 33824413, 2022).
depression (continued). "Patients suffering from generalized anxiety, major depression, and other mood disorders commonly exhibit HPA axis hyperactivity, manifested as high concentrations of corticotropin-releasing hormone (CRH) and exacerbated response to adrenocorticotropic hormone (ACTH)." (PMID 33005029, 2021). "Similarly, preclinical evidence has shown depressive-like behaviors and elevated serum levels of CRH, ACTH, and corticosterone in an animal model of depression induced by unpredictable chronic mild stress." (PMID 34804417, 2021). "In line with our results, an association between remission and significantly higher cortisol response in the DEX/CRH test at baseline has been shown in male but not in female patients with depression." (PMID 33447872, 2021). "In an animal model of depression using the forced swimming test, rats exposed to this chronic stressor showed significant decreases in the plasma levels of both BDNF and motilin, which occurred in parallel with increases in CRH and cortisol." (PMID 34575041, 2021). "In addition, increased levels of plasma and cerebrospinal CRH, plasma cortisol, and episodes of ACTH secretion were also reported in patients with major depression." (PMID 34804417, 2021). "Abundant evidence also confirms early observations of depression-related disturbances in the stress axis (including cortisol hypersecretion, impaired negative feedback, and corticotropin-releasing hormone (CRH) dysregulation)." (PMID 34663459, 2021). "REST can also repress expression by binding to RE1 sites, which can be found on the regulatory elements of the corticotropin-releasing hormone gene, CRH and brain-derived neurotrophic factor (BDNF) genes, among others; both genes are important in stress and depression." (PMID 31740756, 2020). "The dysfunction of hypothalamic–pituitary–adrenal (HPA) axis, the increased secretion of corticotropin-releasing hormone (CRH), the impaired responsiveness to glucocorticoids, the increased size and activity of the pituitary were found in patients in depression patients." (PMID 33329133, 2020). "Depression-like behavior was also not significantly altered by silencing (Gi: 194 ± 10 sec immobile; Control: 198 ± 9 sec immobile) or ablating CRH neurons (DTA: 209 ± 20 sec immobile; Control: 218 ± 16 sec immobile) (data not shown)." (PMID 29346425, 2018). "Remarkably, the total number of CRH-immunoreactive neurones is four times higher in depressed patients compared to healthy individuals despite an overall reduction in total PVN neurone numbers (50%) in major depression and bipolar patients." (PMID 30034342, 2018). "Our current finding indicates a trend of correlation between the severity of depression and the response to the DEX/CRH test; however, the diagnostic categories did not sufficiently fit the biological assessment." (PMID 27582123, 2016). "In (CRH) stimulation tests among these women, those with a history of childhood abuse without depression exhibited increased ACTH responses along with normal-to-decreased cortisol responses." (PMID 24695633, 2014). "The central CRH system plays a pivotal role in the relationship between ELS and depression." (PMID 24596569, 2014). "Several studies have also demonstrated a hypoactivity of the HPA axis, a lower activity of CRH, hypocortisolism, and a decrease in activity of afferent noradrenergic pathways in depression with atypical features." (PMID 24478730, 2014). "In depression and PTSD, increased CRH levels in CSF have been found, which may relate to the dysregulation of signal transduction via the two receptors." (PMID 23422934, 2013). "Interestingly, Xiangshao granule treatment significantly decreased the serum levels of CRH, CORT and ACTH in the depression mouse model (P < 0.05)." (PMID 24367385, 2013).
depression (continued). "Collectively, our study demonstrates that Xiangshao granule has a significant antidepressant effect in the mouse depression model with its desired therapeutic effect possibly achieved through increasing hippocampal BDNF and TrkB expression and downregulating serum CRH, CORT, and ACTH levels." (PMID 24367385, 2013). "Indeed, these receptors appear to be responsible for the sleep impairing effects of CRH, since administration of their antagonist, R121919, improves NREM sleep in an animal model of depression and in depressive patients." (PMID 23667630, 2013). "A subpopulation of patients with major depression and post-traumatic stress disorder (PTSD) have elevated levels of CRH in their cerebrospinal fluid Moreover, HPA axis hyperactivity is the most commonly observed neuroendocrine change in major depressive disorder (MDD)." (PMID 23077729, 2012). "For instance, HPA axis overdrive, related to an enhanced secretion of CRH and an impaired negative feedback via GC receptors, is most consistently observed in patients with psychotic depression." (PMID 21435199, 2011). "Despite this hypercortisolism, patients with MS showed normal, rather than blunted, plasma ACTH responses to ovine CRH, suggesting that the pathophysiology of hypercortisolism in MS is different from that in depression." (PMID 20929574, 2010). "CRH binds to CRHR1 (CRH receptor 1) in the hypothalamus, which is responsible for depression-like behaviour; therefore, inhibiting CRHR1 activity may provide novel psychopharmacological therapeutics for depression." (PMID 36624454, 2023). "Of the five studies in which the cutoff value was 13 or higher, two demonstrated a significant correlation between blood CRH and postpartum depressive symptoms or EPDS score, and one demonstrated a positive correlation between morning cortisol level and severity of depression." (PMID 35903273, 2022). "In this study, we used a mouse model of corticosterone (CORT)-induced depression, and found that EOP had a significant antidepressant effect on the symptoms of CORT-induced depression in mice, and significantly down-regulated the levels of CRH, ACTH and cortisol in the brain tissues of mice." (PMID 36188568, 2022). "An elevated neuroendocrine response to the combined DEX/CRH test can be detected during an acute depressive episode, but it fails to represent specificity in depression given that this response is common to other psychiatric disorders as well as several medical conditions." (PMID 34071053, 2021). "It has been shown, for example, that cortisol response in the combined dexamethasone suppression/corticotropin releasing hormone stimulation test is attenuated in both, past and recent suicide attempters compared to suicide ideators or non-suicidal patients in major depression." (PMID 32256412, 2020). "These evidences show the effect of excessive insulin on CRH may indicate its negative impact on depression." (PMID 32281722, 2020). "The corticotrophin releasing hormone [CRH] increase observed in SSRI treated women may, in part, be due to depressive illness, but higher CRH levels are reported in women prescribed SSRIs than those with unmedicated depression." (PMID 31738813, 2019). "Importantly, D2 antagonism in the hypothalamus may suppress HPA axis hyperactivity by reducing corticotropin-releasing hormone (CRH) secretion, thereby improving sleep continuity and reducing nocturnal awakenings, a key feature of depression-related sleep disturbances." (PMID 41040935, 2025). "So the administration of asiaticoside to depression-like mice restored the composition of the gut microbiota, could improve intestinal permeability and blood-brain barrier integrity, then could decrease the levels of IL-6, TNF-α, CRH, and CORT and increase hippocampal BDNF levels." (PMID 39494347, 2024).